MIR3610 (microRNA 3610)
Synonyms: hsa-mir-3610; mir-3610
Gene: MicroRNA gene on chromosome 8 (116,874,728 to 116,874,800, reverse strand). Ensembl gene ENSG00000283956.
Homologues: Orthologues: chimpanzee MIR3610 (100% identical), macaque MIR3610 (100% identical).